OR1L1 (olfactory receptor family 1 subfamily L member 1)
Description:
Odorant receptor.
Synonyms: OR9-C; OR1L2; HG23; OR9-27
Tractability: Antibody: UniProt places it where antibodies can reach, with medium confidence; UniProt predicts a signal peptide or a membrane-spanning region; its Gene Ontology location is reachable by antibodies, with medium confidence.
Gene: Protein-coding gene on chromosome 9 (122,661,566 to 122,662,648, forward strand). Ensembl gene ENSG00000173679.
Subcellular location: Cell membrane
Pathways (Reactome):
Sensory Perception: Expression and translocation of olfactory receptors
Gene Ontology:
Molecular function: olfactory receptor activity; G protein-coupled receptor activity
Biological process: signal transduction; detection of chemical stimulus involved in sensory perception of smell; G protein-coupled receptor signaling pathway
Cellular component: plasma membrane; membrane
Genetic constraint (gnomAD): Loss-of-function variants: 0 observed, 0.5 expected, observed/expected ratio (o/e) 0, 90% interval 0 to 1.83. That is too few expected variants to judge how well the gene tolerates losing a copy. Missense variants: 367 observed, 390.63 expected, observed/expected ratio (o/e) 0.94, 90% interval 0.86 to 1.02. Synonymous variants: 132 observed, 147.08 expected, observed/expected ratio (o/e) 0.9, 90% interval 0.78 to 1.04.
Homologues: Orthologues: chimpanzee OR1L1 (99% identical). Paralogues in human: OR1L3 (78% identical), OR1L8 (69% identical), OR1L6 (68% identical), OR1L4 (68% identical), OR1F1 (54% identical), OR1M1 (53% identical), OR1E1 (52% identical), OR1J2 (52% identical), OR1J4 (52% identical), OR1J1 (52% identical), OR1E2 (51% identical), OR1G1 (51% identical), and 116 more.